IGKV1-6 (immunoglobulin kappa variable 1-6)
Description:
V region of the variable domain of immunoglobulin light chains that participates in the antigen recognition. Immunoglobulins, also known as antibodies, are membrane-bound or secreted glycoproteins produced by B lymphocytes. In the recognition phase of humoral immunity, the membrane-bound immunoglobulins serve as receptors which, upon binding of a specific antigen, trigger the clonal expansion and differentiation of B lymphocytes into immunoglobulins-secreting plasma cells. Secreted immunoglobulins mediate the effector phase of humoral immunity, which results in the elimination of bound antigens. The antigen binding site is formed by the variable domain of one heavy chain, together with that of its associated light chain. Thus, each immunoglobulin has two antigen binding sites with remarkable affinity for a particular antigen. The variable domains are assembled by a process called V-(D)-J rearrangement and can then be subjected to somatic hypermutations which, after exposure to antigen and selection, allow affinity maturation for a particular antigen.
Synonyms: IGKV16; L11
Gene: Immunoglobulin variable (V) gene on chromosome 2 (88,966,262 to 88,966,767, reverse strand). Ensembl gene ENSG00000239855.
Subcellular location: Secreted; Cell membrane
Gene Ontology:
Biological process: immune response
Cellular component: extracellular region; immunoglobulin complex; plasma membrane
Homologues: Orthologues: chimpanzee IGKV1-6 (85% identical), mouse Igkv15-103 (73% identical). Paralogues in human: IGKV1-17 (94% identical), IGKV1-39 (91% identical), IGKV1D-13 (91% identical), IGKV1D-39 (91% identical), IGKV1OR2-108 (90% identical), IGKV1-12 (89% identical), IGKV1-9 (89% identical), IGKV1-16 (88% identical), IGKV1D-12 (88% identical), IGKV1D-16 (88% identical), IGKV1-27 (87% identical), IGKV1-8 (87% identical), and 81 more.
Diseases named in the same sentence as IGKV1-6 in open-access papers:
IGKV1-6 is named in the same sentence as 6 diseases in open-access papers, as found by Europe PMC text mining. Sharing a sentence is not in itself a finding about the gene and the disease. The quoted sentences say what the papers report.
gingivitis (1 paper, 2025). A disorder involving inflammation of the gums; may affect surrounding and supporting structures of the teeth. "The proteins CD55, GBP6, IGHV3-35, and IGKV1-6 are significant markers in the context of the host response to bacterial infections, particularly in relation to gingivitis and treatment outcomes." (PMID 41156831, 2025).
inflammatory bowel disease (1 paper, 2025). A spectrum of small and large bowel inflammatory diseases of unknown etiology. "Under the condition of inflammatory bowel disease, the expression of Igkv16-104 is related to immune regulation and it should connect with IL6 expression." (PMID 41373555, 2025).
inflammation (1 paper, 2025). Aberrant reaction of the microcirculation characterized by movement of fluid and leukocytes from the blood into extravascular tissues. "Intestinal inflammation should stimulate macrophages/Th17 to secrete IL-6, which then activates the JAK-STAT3 pathway of B cell, thereby upregulating the Igκ enhancer expression (like Igkv16-104) and promoting antibody secretion, thereby exacerbating inflammation or tissue damage." (PMID 41373555, 2025).
IGKV1-6 also shares sentences with these, for which no sentence is quoted: bacterial infections (1 paper); colon cancer (1); lymph node metastasis (1).